IL6 (interleukin 6)
Diseases named in the same sentence as IL6 in open-access papers (continued):
Sharing a sentence is not in itself a finding about the gene and the disease.
liposarcoma (18 papers, 2008 to 2025). A usually painless malignant tumor that arises from adipose tissue. "For instance, miR92a-3p is secreted by tumor cells and stimulates tumor-associated macrophages to produce IL6, a pro-inflammatory cytokine, subsequently promoting the progression of liposarcoma." (PMID 32917956, 2020). "Strong expression of the tumor associated IL-6 was confirmed in liposarcoma cells." (PMID 19025608, 2008). "Both miRNAs were found to stimulate the tumour-associated macrophages (TAM) to secrete pro-inflammatory cytokine, interleukin-6 (IL-6), which in turn promote liposarcoma cell growth, invasion, and metastases." (PMID 39736850, 2025). "Particularly, H3K9me2 has been reported as an epigenetic regulator of TNFα, IL-6, and IL-1β in the human-derived liposarcoma cell line SW872 stimulated with LPS." (PMID 39768289, 2024). "Liposarcoma tissues showed higher IL6 expression with the highest IL6 expression found in DDLPS tissue." (PMID 35313831, 2022). "Some studies showed that TLR7 interacts with miR-25-3p, thereby stimulating the secretion of IL6 by macrophages and promoting the growth and spread of liposarcoma." (PMID 34026613, 2021). "Likewise, EVs from liposarcoma contain miR-25-3p and miR-92a-3p, which stimulate interleukin 6 (IL-6) secretion by macrophages, ultimately increasing tumor cell invasiveness." (PMID 40574836, 2025). "Notably, Panx1 transcription was tightly correlated with IL-6 gene expression in both primary human liposarcomas and clinical tumor tissues." (PMID 37696858, 2023). "In liposarcoma, exosomal miR-25-3p and miR-92a-3p produced by liposarcoma cells could induce tumor-associated macrophages to secrete IL6 via TLR7/8-dependent pathway, thereby enhancing the proliferation and invasion of liposarcoma cells." (PMID 34692482, 2021). "Furthermore, miR-25-3p- and miR-92a-3p-rich exosomes from human liposarcoma cell lines were observed to induce IL-6 secretion by TAMs, leading to an increase in liposarcoma cellular proliferation." (PMID 29515996, 2018). "Moreover, Dox elevated IL-6 expression in primary human liposarcoma cell cultures." (PMID 37696858, 2023).
myelofibrosis (18 papers, 2013 to 2025). A partial or complete replacement of the bone marrow stroma by fibrous tissue. "We concluded that when JAK2 inhibitors are used to treat myelofibrosis, they also inhibit IL-6-induced JAK2-related signal transduction in the lungs to achieve therapeutic effects." (PMID 39659792, 2024). "This mutation correlates with elevated levels of IL-1RA, IL-2R, IL-6, IL-12, IP-10, hepatocyte growth factor, and monokine induced by IFN-γ in primary myelofibrosis patients." (PMID 32341381, 2020). "Ruxolitinib alleviates constitutional symptoms of myelofibrosis (MF) by downregulating interleukin (IL)-1b, IL-6 and TNF-α." (PMID 30700842, 2019). "Independently of JAK status or of MPN subtype (myelofibrosis or PV), several cytokines were reduced after ruxolitinib treatment such as IL1Ra, IL6, IL8, TNFα, and bFGF." (PMID 26525644, 2015). "We hypothesize that tumor cells secreting IL-6 may have been responsible for the development of myelofibrosis in this patient." (PMID 35280806, 2022). "Interestingly, we found that ruxolitinib, a specific JAK1/2 inhibitor which used for myelofibrosis treatment, could substantially reduce plasma IL-6, IL-1β, IFN-γ and TNF-α contents in atherosclerotic rabbits." (PMID 32169038, 2020). "Selinexor has also been shown to reduce the plasma levels of many key pro-inflammatory cytokines (e.g., IL-6, TGFβ, IL-1β, IL-10, IFN-γ, TNF-α) in patients with myelofibrosis, and also in ex vivo studies with PBMCs." (PMID 40565816, 2025). "It was characterized by interleukin (IL)-6, IL-18, IL-18 binding protein (BPa), and CXCL9 chemokine hypercytokinemia accompanied by myelofibrosis." (PMID 37347054, 2023). "Studies about inflammatory cytokines indicated that the levels of IL6, IL2, and sIL2a were elevated during the progression from PV/ET to myelofibrosis." (PMID 36061178, 2022). "The pathologic role of these cytokines is undetermined but their increase correlates with disease prognosis, in particular elevation of IL-6, IL-2R, IL-1RA, MIP-1α, MIG, IL-8, IL-12, IP-10 correlate with shortened primary myelofibrosis survival." (PMID 24116232, 2013). "We identified a set of inflammatory cytokines, including IL-1alpha, IL-4, IL-6, IL-7, IL-9, IL-15 and TNF-alpha, which are elevated in the serum of JAK2V617F mice, similar to the alterations in circulating cytokines observed in patients with myelofibrosis." (PMID 40386398, 2025). "This may explain interstitial pneumonia in myelofibrosis and how treatment with JAK2 inhibitors to block the IL-6-mediated JAK2 downstream signaling pathway also blocked the final inflammatory reaction in the lung." (PMID 39659792, 2024). "Moreover, a correlation between symptomatic reduction of the spleen size in myelofibrosis and reductions of IL-1ra, MIP-1β, IL6, and TNFα was observed." (PMID 26525644, 2015). "Patients with primary myelofibrosis, with or without the presence of JAK2V617F, develop a proinflammatory cytokine signature that contains IL-6, MCP-1, MIG, MIP-1α, TNF-α and IP-10." (PMID 24116232, 2013).
retinal diseases (18 papers, 2011 to 2025). "IL-6 is a key mediator in retinal disease progression, promoting vascular inflammation and impairing endothelial cell function." (PMID 40332248, 2025). "A large number of studies have shown that IL-6 plays a key role in the development of retinal diseases, including DR." (PMID 40265439, 2025). "The level of IL-6 is related to the severity of retinal diseases, while COX2 participates in disease progression by regulating inflammation and angiogenesis." (PMID 40717982, 2025). "Six of the included studies reported the effects of resveratrol on IL-6 levels in animal models with retinal disease (experimental group, n = 34; control group, n = 34)." (PMID 40717982, 2025). "This new model will allow us to isolate the specific effects of IL-6 trans-signaling in Müller glial cells and differentiate the roles of classical and trans-signaling in retinal disease." (PMID 36271280, 2022). "The roles of angiogenic and proinflammatory factors, including VEGF, TNF, TGFB1, CASP3, IL6, IFNG, and IL1B, and their association with miRNAs and the specified proteins in retinal diseases have been previously reported." (PMID 36180575, 2022). "ARPE-19 cells, a human RPE cell line, express increased levels of angiogenic cytokines, such as VEGF and IL6, involved in various retinal diseases in response to cyclic mechanical stress." (PMID 32355505, 2020). "Furthermore, cytokine inhibitors, such as TNF-α blockers (adalimumab, infliximab), IL-6 antagonists (tocilizumab), and IL-1β inhibitors (canakinumab), are being actively explored for their potential to reduce chronic inflammation in retinal diseases." (PMID 40722794, 2025). "Clinical studies have mainly focused on the role of IL-6 in retinal diseases." (PMID 39759107, 2024). "For instance, in a study involving mice subjected to ischemia-reperfusion injury, topical application of caffeine led to the preservation of brain-derived growth factor levels and a decrease in IL-6 mRNA expression, indicating caffeine's potential to mitigate inflammation in retinal diseases." (PMID 39502492, 2024). "Inflammatory cytokines such as interleukin-6 (IL-6) are closely connected to retinal diseases." (PMID 21076532, 2011). "Our findings position PEDF as a novel antagonistic agent of IL-6 production in RPE cells, underscoring its use for the management of retinal disease-related inflammation." (PMID 36467689, 2022). "We discuss PEDF as a novel agent for potential use in retinal disease-related inflammation management due both to its presence in the RPE, and its role in suppressing IL-6." (PMID 36467689, 2022). "Among the inflammatory pathways enriched in our analysis, the IL6, JAK-STAT, TNFα, and NF-κB pathways exacerbate the pathology of retinal disease." (PMID 32735610, 2020). "The increased expression of IL-6 and OSM in retinal diseases, such as DR and AMD, may reflect a failure of anti-inflammatory pathways to properly regulate chronic low-grade inflammation, which is a key feature in the progression of these diseases." (PMID 39759107, 2024).
sickle cell disease (18 papers, 2009 to 2025). Sickle cell anemias are chronic hemolytic diseases that may induce three types of acute accidents: severe anemia, severe bacterial infections, and ischemic vasoocclusive accidents (VOA) caused by sickle-shaped red blood cells obstructing small blood vessels and capillaries. "Similarly, IL-6 has been implicated as a marker of endothelial activation in vascular inflammation of transgenic sickle cell mice and vaso-occlusive crises of sickle cell disease patients." (PMID 35563154, 2022). "We found that apart from being a nociceptive agent, flurbiprofen exerts a strong anti-inflammatory effect by suppressing NF-κB signaling, which was evidenced by reduced levels of TNF-α and IL-6 in wild-type and sickle cell disease Berkeley mice models." (PMID 37180702, 2023). "High levels of IL-6 and CXCL8 are also associated with poorer clinical outcomes in sickle cell anemia." (PMID 36232655, 2022). "We now report significantly higher levels of IL-6 mRNA and protein in hearts of the Townes sickle cell disease (SS) mice (2.9-fold, p ≤ 0.05) than control mice expressing normal human hemoglobin (AA)." (PMID 32973791, 2020). "Additionally, hypermetabolism in haemoglobin SS, elevated interleukin-6 levels (which may suppress appetite), and increased resting energy expenditure contribute to micro- and macro-nutrient deficiencies, underscoring the need for nutritional replacement in sickle cell anaemia management." (PMID 41175423, 2025). "Tocilizumab, an activity blocker for Interleukin-6 (IL-6), a critical inflammatory/immune-mediated cytokine in macrophage activation, was used as a salvage treatment in a few cases of hyperhemolysis syndrome in sickle cell disease." (PMID 40722584, 2025). "Similarly, RVX treatment decreased MCP-1 plasma levels and MMP-9 protein levels in the external jugular vein of mice following catheter thrombosis, as well as IL-6 plasma level and neutrophil levels in a mouse model of sickle cell disease." (PMID 33301454, 2020). "Likewise, increased exposure to inflammatory cytokines such as interleukin-6 and tumor necrosis factor-α and angiogenic factors such as PDGF and VEGF has been associated with altered cardiac function in settings other than sickle cell disease." (PMID 19956689, 2009). "In a mouse model of sickle cell disease (SCD), S1P receptor activation leads to significantly elevated IL-6 levels involved in severe chronic inflammation and tissue damage." (PMID 38523645, 2024). "Sickle cell disease patients showed significantly higher markers of endothelial function (TNF-α, IL-6, and IL-17A) in comparison to controls (p-values < 0.001, < 0.001, and 0.006, respectively)." (PMID 39354381, 2024). "It is well-known that hydroxycarbamide (hydroxyurea), a cytoredutor drug indicated for MPN treatment, is capable of lowering serum inflammatory markers such as TNF-α, IL-6, CXCL8, and IL-1β in sickle cell disease patients." (PMID 34084749, 2021). "Regarding sickle cell disease, previous evaluation of monocytes subsets has identified that non-classical or patrolling monocytes express low levels of TNF-α and IL-6 and they seem to be important protecting the microvasculature from VOE35." (PMID 31616024, 2019). "Sickle cell disease patients with more severe genotypes (SS and Sβ0) had slightly greater levels of markers of endothelial function (TNF-α, IL-6, and IL-17A) than Sβ+ patients, but the difference was not statistically significant (p-values = 0.173, 0.583, and 0.720, respectively)." (PMID 39354381, 2024).
skin aging (18 papers, 2019 to 2025). The gradual irreversible changes in structure of skin that occur as a result of the passage of time.. "In skin aging, it has been shown that IL-8 and IL-6 are clearly linked to MMPs modulation and COL1A1 gene and protein expression." (PMID 31001530, 2019). "Taken together, these findings suggest that the coordinated actions of PPARG, ESR1, and IL6 could serve as promising molecular targets of OFSO for counteracting skin aging hair loss disorders." (PMID 41516153, 2025). "Furthermore, L3R inhibits pro-inflammatory cytokines, such as IL-6 and IL-8, which stimulate diverse inflammatory reactions associated with skin aging." (PMID 37507970, 2023). "IL‐6 is a cytokine associated with inflammation and aging, and an elevated expression level of IL‐6 is a notable characteristic of the inflammatory response and skin aging." (PMID 40367094, 2025). "Excessive accumulation of inflammatory cytokines such as IL-1β and IL-6 induces inflammatory responses in the skin, accelerating skin aging." (PMID 40136442, 2025). "We focused on MMP-1, COX-2, and IL-6 to elucidate the molecular mechanisms by which luteolin mitigates PM-induced skin aging and inflammation." (PMID 40374763, 2025). "By week 8, the levels of IL-1β and IL-6 were significantly higher in the HSD group compared to the ND group in this study, indicating that skin aging associated with high salt intake is closely related to inflammation." (PMID 39465002, 2024). "Many current studies have shown the role of SASP in skin aging, highlighting factors including IL-6, IL-8, IFN-γ and such." (PMID 39316420, 2024). "The results suggested that LNF is non-toxic to dermal fibroblast cells and can inhibit the secretion of MMP1, MMP9, IL-6 and IL-8 upon UV-induced skin aging." (PMID 35215366, 2022). "Modulating IL-6 and IL-8 is an important strategy to prevent or delay skin aging." (PMID 39275030, 2024). "Together, these results indicated that LNF could potentially inhibit UV-mediated IL-6 and IL-8 production, and subsequently prevent photo-stimulated skin inflammation and skin aging." (PMID 35215366, 2022). "This phenomenon can aggravate skin aging by secreting SASPs such as IL-6 and IL-8." (PMID 35889225, 2022). "In skin aging, IL-6 is a regulator correlated with the generation of wrinkles on the skin, whereas COX-2 is well known to mediate the synthesis of prostaglandin E2 (PGE2), a lipid-derived signaling molecule involved in the production of MMP-1 and the suppression of collagen biosynthesis in HDFs." (PMID 34679744, 2021). "Future studies should also evaluate the efficacy of chalcone 1 in both in vitro and ex vivo human models of skin aging, focusing on its impact on downstream inflammatory mediators such as PGE2, IL-1β, and IL-6, to further substantiate its potential." (PMID 40710503, 2025). "IL-6, IL-1β, TNF-α and Col-I are the important cytokines in the pathological mechanism of skin aging." (PMID 37927602, 2023). "An increase in pro-inflammatory cytokines, such as IL-1, IL-6 and TNF-α, is generally observed with skin aging." (PMID 34573004, 2021). "Kisspeptin-E suppressed UV-induced 11 beta-hydroxysteroid dehydrogenase type 1 (11β-HSD1) stimulation leading to a regulation of skin aging related genes, including type I procollagen, matrix metalloproteinases-1 (MMP-1), interleukin-6 (IL-6), and IL-8, and rescued the skin integrity." (PMID 33182726, 2020).
skin infection (18 papers, 2011 to 2025). An inflammatory process affecting the skin, caused by bacteria, viruses, parasites, or fungi. "Furthermore, we aimed to assess the effect of PF in controlling the inflammatory process associated with skin infection by MRSA by measuring pro-inflammatory cytokines (IL-6)." (PMID 34489917, 2021). "In line with this, in our model of skin infection with C. albicans, an inflammatory, innate response was observed and characterized by the increased secretion of IL-6 and IL-8 into the CCM." (PMID 35499318, 2022). "Skin infections caused by S. aureus are related to the exacerbated production of pro-inflammatory cytokines as a tumor necrosis factor-α (TNF-α) and IL-6." (PMID 36313341, 2022). "We investigated the immune-modulatory activity of celecoxib in MRSA skin infection by measuring the levels of the inflammatory cytokines IL-6, TNF-α, IL-1β, and MCP-1 using ELISA." (PMID 26284040, 2015). "In addition, it reduced the bacterial load and regulated the levels of inflammatory cytokines IL-6 and IL-10 at the wound site in a mouse skin infection model." (PMID 40572502, 2025). "The two strains also induced significant difference in IL-6 production at skin infection sites." (PMID 26047469, 2015). "For example, keratinocytes infected with SLO-deficient mutants of S. pyogenes exhibited reduced production of the proinflammatory cytokines IL-1β, IL-6 and IL-8 compared to wildtype S. pyogenes, and SLS can induce the production of IL-1β during skin infection." (PMID 38452154, 2024). "They found that CEMIP loss increases inflammation and antimicrobial activity following a skin infection and that CEMIP−/− mice challenged with S. aureus had higher IL-6 and neutrophil infiltration." (PMID 36902251, 2023). "In C. albicans infection, the cytokines IL-6, TNF-α, interleukin-12 (IL-12), interferon-γ (IFN-γ) and interleukin-17 (IL-17) appear in the initial stage of skin infection." (PMID 35053737, 2022). "More recently, MG extract is shown to possess antibacterial activity against S. aureus and dramatically downregulate the expression of TH1 cytokines, namely TNF-α, IL-6, and IL-1β, via the TLR-2 pathway in a skin infection model of mice." (PMID 30959963, 2019). "Proinflammatory cytokines and chemokines, such as IL-1α, IL-6, TNFα, and CXCL8, secreted by various cell types play a fundamental role in attracting neutrophils and T cells to the place of skin infection." (PMID 21619700, 2011). "Levels of the proinflammatory cytokines IL-1, IL-6, and TNF-α were elevated during wound healing, consistent with previously reported results showing elevated IL-1, IL-6, IL-10, TNF-α, IL-2, IL-8, IL-13 and granulocyte colony-stimulating factor (G-CSF) in the skin infection wound model." (PMID 36901790, 2023). "Furthermore, ebselen has been shown to exhibit potent anti-inflammatory activity in two rodent models of MRSA skin infection reducing the expression of key cytokines (TNF-α, IL-1β, and IL-6) that impair wound healing." (PMID 33617589, 2021). "The results showed that DPTM could promote the healing of MRSA skin infection, reduce the bacterial burden of infected skin MRSA and decrease the secretion of IL-6 and TNF-α inflammatory cytokines in plasma." (PMID 34071703, 2021).